ALB (albumin)
Diseases named in the same sentence as ALB in open-access papers (continued):
Sharing a sentence is not in itself a finding about the gene and the disease.
cancer (continued). "Symptom-specific treatment with diuretics and albumin was ineffective in the case of our patient; however, the CLS remitted promptly with cancer-specific therapy." (PMID 39272709, 2024). "The present study aimed to evaluate the levels of biomarkers, such as glutathione (GSH) in the blood, as well as serum albumin and total protein levels in SLT users with oral precancerous and cancerous lesions." (PMID 38476986, 2024). "Their multicenter retrospective analysis revealed that a preoperative low albumin-to-fibrinogen ratio (AFR) serves as a prognostic biomarker for poorer time to progression (TTP), overall survival (OS), and cancer-specific survival (CSS)." (PMID 39281816, 2024). "Collectively, our study positions albumin-hitchhiking, nanobody-STING agonist conjugates as an enabling, multimodal, and programmable platform for cancer immunotherapy with high translational potential." (PMID 38766114, 2024). "In all, 356,554 participants were kept in the main analysis after excluding participants under the age of 18, those with prevalent cancer, those with less than one year of follow-up, and those with missing data in CRP, ALB, GLO, PLA, and WBC." (PMID 39314636, 2024). "Recently, a novel prognostic index based on albumin and ALP levels, the albumin-to-ALP ratio (AAPR), was proposed in a variety of cancers." (PMID 38698782, 2024). "The neutrophil-percentage-to-albumin ratio (NPAR), a novel inflammatory biomarker, has been used to predict the prognosis of patients with cancer and cardiovascular disease." (PMID 39102412, 2024). "Several prognostic scores have been developed to aid in the assessment of cancer prognosis, some of which are based on serum CRP and albumin levels, such as the Glasgow prognostic score." (PMID 37173358, 2023). "Since its inception, the Hemoglobin, Albumin, Lymphocyte, Platelet Score (HALP) has gained attention as a new prognostic biomarker to predict several clinical outcomes in a multitude of cancers." (PMID 36848404, 2023). "Our results also revealed that albumin–CGA nanoparticles possess significant anti-microbial and anti-cancer properties during in vitro experiments with MDA-MB-435s cells." (PMID 37176983, 2023). "Human serum albumin (HSA) binds many natural ligands and serves as a major nutrient source that is rapidly consumed and metabolized by proliferative cancer cells." (PMID 37657447, 2023). "For example, multiple studies have consistently reported a lower level of plasma albumin and an increased level of alpha-1-acid glycoprotein (AGP) in various cancer types." (PMID 38140068, 2023). "The potential of GINI is linked to the incorporation of two nutritional indices, namely albumin and CRP, which are also recognized as indicators of cancer cachexia." (PMID 37760482, 2023). "Recent studies have shown that CAR is a more accurate indicator than albumin and hs-CRP alone in terms of the evaluation of systemic inflammatory status as well as the determination of prognosis of patients with cancer and critical illness." (PMID 36747210, 2023). "Meanwhile, on the basis of ALB, GLB, and AGR, the AGS has been proposed as another novel model to predict the prognosis of cancer." (PMID 36983238, 2023). "The results confirm that with albumin, age, resection type, perineural invasion, and ratio of metastatic lymph nodes, T and TNM stages were significant predictors of cancer-specific survival (CSS)." (PMID 37007147, 2023). "In this work, we designed a nanocapsule HHSA@Ce6-DOX based on flexible hollow human serum albumin nanocapsule (HHSA) and loaded photosensitizer Chlorin e6 (Ce6) and chemotherapeutic drug Doxorubicin (DOX) for synergistic cancer therapy." (PMID 36798745, 2023). "Albumin nanoparticles are involved in the delivery of DOX, Abraxane, curcumin and tacrolimus involved in cancer treatment." (PMID 36850121, 2023).
cancer (continued). "In fact, enhanced CRP is one component of the Glasgow prognostic score, which is a cumulative inflammation-based cancer prognostic marker composed of CRP elevation and a decrease in albumin concentration." (PMID 36441359, 2023). "In contrast to malnourished patients with other types of cancer, we observed relatively few patients with low BMI, FFMI, and serum albumin in our cohort of patients." (PMID 36839402, 2023). "Albumin-to-globulin ratio (AGR) and the prognostic nutrition index (PNI) are often used to assess the immunonutritional status of cancer patients." (PMID 37828259, 2023). "Patients with active cancer showed multiterritorial infarcts more frequently, and usually presented with higher D-dimer, CRP, LDH, and INR and lower albumin, Hb, LDL cholesterol, total cholesterol and thrombocytes." (PMID 37021282, 2023). "Consequently, the albumin level may be an indicator of cancer prognosis." (PMID 36950094, 2023). "In order to find a cost-effective prognostic biomarker for cancer patients, biochemical markers of inflammation (leucocytes and their subtypes, levels of some cytokines, CRP, albumin) have been incorporated in prognostic factors for numerous types of cancer." (PMID 37108738, 2023). "In this study, we synthesized flexible hollow human serum albumin (HHSA) and loaded photosensitizer Chlorin e6 (Ce6) and the chemotherapeutic drug Doxorubicin (DOX) for synergistic cancer therapy." (PMID 36798745, 2023). "Although ALB and GLB are important predictive factors in many malignant tumors, their serum levels are affected by many factors, such as stress response, liver insufficiency, and alteration of body fluid volume." (PMID 36983238, 2023). "This predictor, Index4, is easily calculated by 2 laboratory values, albumin and creatinine clearance, as well as ECOG PS and stage of the cancer." (PMID 36658198, 2023). "For example, several proteins were pan-cancer markers present in EVs from nearly all PDX models, including ALB, C1QBP, CDH1, and PKM." (PMID 36470535, 2023). "Specifically, the external validation data included six variables among the top seven predictive variables, including age, preoperative albumin, preoperative NRI, the difference in the percentage of haemoglobin, cancer stage, and 1 year postoperative NRI." (PMID 36775841, 2023). "CAR is a significant inflammatory biomarker for assessing prognosis in patients with certain cancer, and has been shown to have a better predictive value than hs-CRP and albumin alone in terms of ischemic events." (PMID 36747210, 2023). "Evidence indicates that albumin interacts with and regulates ECM components, potentially inhibiting cancer cell invasion and metastasis." (PMID 37987317, 2023). "During our latest studies on the albumin homeostasis of cancer cells, we discovered that CT26 cells have a distinctly higher albumin uptake compared to B16 cells." (PMID 36839999, 2023). "Combining lymphocyte count and serum albumin levels, PNI is considered to reflect both cancer-related malnutritional status and cancer-related immune status." (PMID 36831069, 2023). "In addition to the Cancer Cachexia Risk Score, the Geriatric Nutritional Risk Index (GNRI) may benefit from early detection of nutritional risk by utilizing the clinically available data on weight and albumin level." (PMID 37571328, 2023). "The systemic inflammation score (SIS), based on preoperative lymphocyte to monocyte ratio (LMR) and albumin (ALB), was recently developed and is demonstrated to be a novel prognostic indicator in several cancers." (PMID 36313652, 2022). "The distribution of age, sex, cancer types, comorbidities, body weight, BMI, nutritional status, HGS, albumin, hsCRP, and IL-6 across the intervention groups were comparable at baseline." (PMID 35276977, 2022). "Patients with cancer cachexia tended to be younger than 65 years old, male, smoker, alcohol drinker, TNM stage III and IV, with lower albumin and higher NLR (all P < 0.001)." (PMID 36476477, 2022).
cancer (continued). "A particular heptamethine cyanine dye (MHI-148) was reported to readily form an adduct with albumin, and MHI-148 can be imported via albumin receptors which are over-expressed on cancer cells." (PMID 35164144, 2022). "For instance, cancer promotes the expression of TNF-α (a pro-inflammatory factor), which can downregulate the transcription of the albumin gene and inhibit albumin synthesis in hepatocytes." (PMID 35719922, 2022). "In several cancers, including CRLM, inflammatory indices such as the neutrophil/lymphocyte ratio (NLR), platelet/lymphocyte ratio (PLR), and C-reactive protein/albumin ratio (CAR) have been indicated to have good prognostic values." (PMID 35915403, 2022). "IL-6 represents the degree of inflammation in cancer tissue, and IL-6 elevation leads to increased CRP and decreased serum albumin." (PMID 36260237, 2022). "To address the effects of pretreatment serum albumin on ICB outcomes, we collected detailed data from 1714 patients treated with ICB across 16 cancer types." (PMID 35393553, 2022). "The main role of albumin, however, in the developed smart DDS, was targeting cancer cells, as many solid tumors are known to promote higher albumin uptake and overexpress albumin-binding proteins." (PMID 35744957, 2022). "As we know, the total protein is the sum of albumin and globulin, so ALB/GLB ratio (AGR) is one of the key indicators in the combination of indicators for screening cancer." (PMID 36547129, 2022). "Genes such FAM182A, SOX9, AHNAK2, ENSG00000121031, FLT3LG, PMEPA1, ZFP36L2 in the large intestine, ALB, KRTAP19-1, APOB, CD200, CRYGD, KRTAP24-1, OR6N2 in the liver are novel predictions, and their functions in these cancers can further be studied." (PMID 34997044, 2022). "Additionally, decreased albumin levels demonstrate an increased inflammatory status with elevated levels of cytokines, such as tumor necrosis factor-alpha, IL-1, and IL-6, which may contribute to cancer progression." (PMID 35915403, 2022). "Novel magnetic microspheres composed of a Fe3O4 nanocore, a bovine serum albumin (BSA) matrix, and a rod-like SiO2 nanoshell, which had flagellum-like surface for force-mediated cancer therapy were developed." (PMID 35794559, 2022). "Accumulating evidence has also suggested that hsCRP/LYM, hsCRP/ALB, and prognostic nutritional index (PNI) present powerful prognostic values in many types of cancer." (PMID 36016629, 2022). "The FA-FITC was stably bound to albumin-fused anti-HER2 via hydrophobic interaction, and the albumin-fused anti-HER2 was efficiently uptaken by HER2-overexpressing cancer cells." (PMID 35456562, 2022). "Fibrinogen/albumin ratio(FAR), on the other hand, has prognostic importance like other inflammation indicators in cancer." (PMID 36496365, 2022). "The amount of IL-6 in the circulating blood reflects the cancer state and when IL-6 is elevated, CRP is increased and albumin is decreased." (PMID 36260237, 2022). "Lower levels of albumin and higher levels of FIB and D-dimer were shown in the CAD + /cancer + group than the CAD-/ cancer-, CAD-/cancer + and CAD + /cancer- groups (all p < 0.05)." (PMID 35463783, 2022). "Since PNI is a combination of lymphocytes and serum albumin, it is easy to understand the relationship between PNI and survival of cancer patients." (PMID 35603156, 2022). "A Pt(IV) prodrug was attached to Human serum albumin (HSA) that protected it from premature reduction before being uptaken by cells and improved cancer targeting efficacy." (PMID 36324675, 2022). "Patients with cancer often have systemic inflammation, and a combination of serum CRP and albumin level is used as a method for evaluating inflammatory response and nutritional status." (PMID 35204642, 2022). "More recently, the fibrinogen-to-albumin ratio (FAR), an inflammation-based model, was suggested as a prognostic maker for various cancer patients." (PMID 35606690, 2022).
cancer (continued). "The controlling nutritional status (CONUT), as an immune-nutritional index deriving from peripheral blood variables of albumin (ALB), lymphocyte (LYM), and total cholesterol (TC), has been reported to be related to prognosis in various cancers, including ESCC." (PMID 36505443, 2022). "We also examined the correlation between IBS using CRP and/or albumin including PNI, CAR, mGPS and cancer prognosis." (PMID 36194563, 2022). "In the univariable analysis, PD‐L1 expression, number of metastatic sites, previous cancer treatment, NLR and PLR ratio, Hb level, and albumin level were found to be significant." (PMID 35785522, 2022). "The advanced lung cancer inflammation index (ALI), which is composed of serum albumin levels, neutrophil-lymphocyte ratio (NLR) and body mass index (BMI), is related with the poor outcomes in patients with different types of cancer." (PMID 36458177, 2022). "Decreased albumin and increased NEFA are both features of cancer and plasma free [Trp] is therefore likely to be elevated in cancer patients." (PMID 36286592, 2022). "However, to our knowledge, there are no previous studies on the association between albumin level and appetite in palliative care cancer patients; neither has anyone studied whether there is a difference between men and women in palliative care." (PMID 35629338, 2022). "The carcinoembryonic antigen (CEA), C-reactive protein (CRP), albumin, D-dimer, activated partial thromboplastin time (APTT), and R2 showed significant differentiation between benign and malignant tumors." (PMID 36359203, 2022). "In the present study, we found that PDAC patients with high SOX8 expression exhibited poor response to albumin-bound paclitaxel chemotherapy through cohort study and validation of our hospital PDAC cancer tissue." (PMID 35173526, 2022). "In cancer therapy, the first protein nanoparticle approved by FDA as a drug carrier for clinical use is the albumin combined with paclitaxel (Abraxane®) for the treatment of metastatic breast cancer." (PMID 34997888, 2022). "The score system of Glasgow prognostic score (GPS) based on ALB and CRP was also confirmed as one of the most widely recognized scores for predicting clinical outcomes in a variety of cancers." (PMID 35300627, 2022). "This suggested that more attention should be paid to biomarkers related to albumin and body weight, such as ALI, NRI, and GNRI, when assessing the nutritional status of patients with cancer." (PMID 36517779, 2022). "GEM-HSA-NP is composed of GEM and albumin, thus, theoretically, after GEM-HSA-NP taken into cancer cells, the degradation of the albumin component within the cell would consume large amounts of ATP." (PMID 35656085, 2022). "Of note, the Glasgow prognostic score, an outcome prediction model for cancer patients, is based on CRP and albumin levels." (PMID 34521927, 2021). "CBC-D weekly×1 month, q2 weeks×2 months→monthly.ALT, AST, GGT, ALP, bilirubin, albumin, INR q3months.Age-related cancer screening and skin checks.Consider testing for thiopurine S-methyltransferase (TMPT) deficiency before initiation." (PMID 34108243, 2021). "GPS is a cumulative inflammation-based cancer prognostic marker based on elevated serum CRP and decreased albumin concentration." (PMID 34677378, 2021). "The results showed that most of the cells extracted from cancer tissue were HCC cells, and hepatocytes highly expressed CK-18, ALB, and ARG-1." (PMID 34776939, 2021). "In the present work, amorphous-titania propyl-amine functionalized (a-TiO2-NH2) NPs, coated with bovine serum albumin (BSA), are stimulated with high energy shock waves to induce cytotoxic effects in cancer cells." (PMID 34575499, 2021). "Cancerous tissue presents increased capillary permeability and retention [EPR] and thus is more readily infiltrated by large particles, including albumin-based drug carriers." (PMID 34959309, 2021).
cancer (continued). "Studies have reported that inflammation-based markers can be used as potential prognostic factors for many cancers, including CRP, neutrophils, lymphocytes, dNLR and ALB." (PMID 34446028, 2021). "Although each of ALB and ALP has own prognostic value in various cancer types, yet AAPR has been shown to be a more powerful prognosticator than either of the ALB and ALP alone." (PMID 33927759, 2021). "Comorbidities, a low albumin level, male sex, and older age are also known to increase the LOS after cancer surgery." (PMID 34885120, 2021). "Human serum albumin (HSA) was used as a drug delivery carrier to construct a drug, and an approachable model is necessary for targeting drug delivery in cancer therapy." (PMID 33928164, 2021). "Moreover, it is reported that albumin coating may improve the internalization in cancer cells." (PMID 34575499, 2021). "PNI is calculated as “albumin level (g/L) + 0.005 × lymphocyte count”, and decreased PNI can affect cancer-related prognosis." (PMID 34360768, 2021). "We noted significant correlations of OS and DFS with overall stage, ENE, cancer cell differentiation, DOI, chemotherapy, serum albumin level, NLR, and ALI." (PMID 34660250, 2021). "The hemoglobin, albumin, lymphocyte and platelet (HALP) score has been confirmed as a prognostic factor in several types of cancers." (PMID 33974528, 2021). "GPS is determined by serum albumin level (cutoff value = 3.5 g/dL) and CRP level (1.0 mg/dL) and is a well-validated prognostic system in patients with advanced cancer." (PMID 34575208, 2021). "Additionally, albumin synthesis may be suppressed even in patients with early stage cancers." (PMID 32754301, 2020). "RNAi-mediated attenuation of Cav-1 expression reduced uptake of albumin and Nab-PTX in cancer cells and rendered them resistant to Nab-PTX-induced apoptosis." (PMID 31858848, 2020). "The inflammation-based Glasgow Prognostic Score (GPS) makes use of the changes in albumin and hypersensitive C-reactive protein (H-CRP) to concisely evaluate the prognosis of cancer patients." (PMID 32355581, 2020). "This is in accordance with clinical tools such as the Glasgow Prognostic Score, a prognostic indicator for various types of cancers calculated with CRP and albumin values." (PMID 32351914, 2020). "It has been reported that bovine serum albumin (BSA) nanoparticles (NPs) serve as carriers for anticancer drugs, which have been extensively explored for their therapeutic efficacy against cancers." (PMID 32796651, 2020). "CAR, as a star prognostic biomarker for cancer, two of whose elements, CRP and ALB, are derived from blood." (PMID 32963635, 2020). "After the endocytosis of cancer cells, FU20‐lipid/albumin complexes would be hydrolyzed by lysosome to release FU20 and inhibited cancer cell proliferation." (PMID 32832360, 2020). "Provide an updated and comprehensive evaluation of the prognostic value of the albumin-fibrinogen ratio (AFR) and the fibrinogen-prealbumin ratio (FPR) for patients with cancer." (PMID 31931816, 2020). "Because levels of both albumin and globulin are easily influenced by factors, such as dehydration or oedema, AGR has been suggested and explored as a prognostic factor in several cancers." (PMID 32967632, 2020). "Albumin-globulin ratio (AGR), a variable based on serum albumin and non-albumin proteins, has been demonstrated as a predictor of mortality in patients with malignant neoplasm." (PMID 32059708, 2020). "Cancer-related proinflammatory cytokines, such as interleukin-6 (IL-6) and interleukin-1 (IL-1), as well as tumor necrosis factor-α (TNF-α) inhibit albumin production, leading to cancer cachexia." (PMID 33176752, 2020). "In this study, the KD-ABC score, composed of ALB, BS, and CRP, was proposed, and it stratified the prognosis of cancer patients treated with the ketogenic diet." (PMID 32438645, 2020).